CD247 (CD247 molecule)
Diseases named in the same sentence as CD247 in open-access papers (continued):
Sharing a sentence is not in itself a finding about the gene and the disease.
tumor (continued). "Besides, patients with low-expression CD247 were more likely to have lower activity of T cells in general, Th1 cells, NK cells, and TIL (tumor-infiltrating lymphocytes) and higher activity of dendritic cells (DCs), M2 macrophages, and neutrophils compared with patients with high-expression CD247." (PMID 34880861, 2021). "Thus, downregulation of ZAP70 and CD247 expression in this pathway may lead to an attenuation of NK cell-mediated cytotoxicity of the tumour, which in turn leads to the occurrence of PTC." (PMID 29967488, 2018). "Key immune activation and tumor suppression genes including CD2, CD3, CD247 (CD3 zeta chain), CD48, CD84, CCL19, CXCL10, and SLAMF6 were consistently upregulated in the hot phenotype across all ancestries." (PMID 41387728, 2025). "Through univariate Cox regression analysis, nine genes, including 3 oncogenes (HTR3C, CRHR2 and AGTR1), 6 tumor suppressor genes (CD8A, CD3E, SERPIND1, CXCR6, BMX and CD247) were proved to be correlated with the overall survival of EC patients." (PMID 38355782, 2024). "A significant top-scoring model (tumour stage, age, CIITA, IKZF3, CD247, TENT5C; likelihood ratio test p = 2 × 10−7) was returned for the MEL_TCGA training set (n = 255, TCGA_TRAIN)." (PMID 35743743, 2022). "The immune-checkpoint genes PD-L1 (CD247), CTLA4, LAG3, TIM3 (HAVCR2) and IDO1 were assessed using gene expression data, with significantly higher expression of each in DDIR-positive tumours." (PMID 34728791, 2022). "Besides, aberrant amplification or deletion event associated with immune checkpoint stimulator genes (CD247, CD274, PD-1, PD-L1, and LAG3) was observed in distinct subgroups, upregulation of which expression could restrict anti-tumor response and facilitate immune escapes." (PMID 33407498, 2021). "CD247 is mainly expressed by tumor-infiltrating macrophages, not by malignant cells, which explains why CD247 is significantly overexpressed in low-risk patients." (PMID 34868310, 2021). "Our results indicated that patients with high CD247 expression (score 2 and 3) had a more favorable prognosis of survival, suggesting that CD247 may be a target for tumor immunity in HNSCC and that drugs targeting CD247 could be a potential therapeutic strategy." (PMID 37955651, 2023). "We could only detect the RNA and protein expression changes of CD3G, but not CD3D, CD3E or CD247 between tumor and normal tissues." (PMID 36176400, 2022). "Together, three tumor antigens (CD247, FCGR1A, and TRRAP) were identified as potential candidates for the CHOL-mRNA vaccine with potential immune provocative effects and can be processed and presented by antigen-presenting cells (APCs) to induce a tumor response." (PMID 33685460, 2021). "Interestingly, the response to CHI was irrespective of CD247 expression within tumor cells." (PMID 33240813, 2020). "Therefore, the low expression of CD247 may promote inflammation in SLE by upregulating the regulation of non-canonical NF-kB signaling transduction and may further affect the immune suppression and tumor progression in DLBCL through changes in the immune microenvironment.." (PMID 41488073, 2025).
cancer (25 papers, 2010 to 2025). A tumor composed of atypical neoplastic, often pleomorphic cells that invade other tissues. "Genes TCRA and CD247, both of which have at least 15 connections in the cancer pain network, encode proteins that are essential to the assembly of the T-cell receptor-CD3 complex at the plasma membrane." (PMID 26872611, 2016). "Collectively, these results identify MSL1 as a key epigenetic regulator of CD247 expression and a potential therapeutic target for enhancing the efficacy of cancer immunotherapy." (PMID 41409271, 2025). "CD247, also known as PD-L1, is widely expressed in various cancer cells and can impair T cell-mediated immune responses." (PMID 40002900, 2025). "In the PD1 and PD-L1 cancer immunotherapy pathway, downregulation of CD247, PDCD1, and CD28 gene expression and upregulation of CD274 and miR-3614-5p were measured." (PMID 38571958, 2024). "Twelve DGs are involved in PD-L1 expression and the PD-1 checkpoint pathway in cancer, including CD247, also known as PD-L1." (PMID 37786776, 2023). "As expected, MYC expressions in the cancer tissues were significantly upregulated, while CD247 and TLR2 were significantly downregulated in the adjacent normal tissues." (PMID 36389789, 2022). "The status of miRNAs from the third group which affect the CD247 gene responsible for the CD3-zeta subunit in cancer tissues relative to adjacent normal tissues." (PMID 24244363, 2013). "Research has shown that CD247 plays a role in the functions of cancer." (PMID 41488073, 2025). "Interestingly, five genes (CD247, CD3E, ZAP70, LCK, PTPN6) were associated with the hsa05235 pathway (PD-L1 expression and PD-1 checkpoint pathway in cancer)." (PMID 34880861, 2021). "Combating MDSCs and chronic inflammation, while monitoring MDSCs and CD247 in T-cells and NK cells, may provide valuable tools for choosing the correct therapeutic regiments and timing while taking into account both the cancer and immune factors." (PMID 26528286, 2015). "Other genes that showed potential association with cancer pain in HNSCC patients included PIK3C2G (rs10770367, p value = 1.10 × 10−3), TCRA (rs6572493, p value = 2.84 × 10−3), PDGFC (rs6845322, p value = 4.88 × 10−3), and CD247 (rs2995082, p value = 7.79 × 10-3)." (PMID 26872611, 2016). "The subnetwork involves an interesting combination of the downregulation of the cancer gene EGFR and the amplification of a group of genes involved in T-cell receptor signaling (PTPRC, CD247, and ARPC5)." (PMID 30978274, 2019). "The first generation typically consisted of the extracellular, cancer cell-targeting scFv fused to the CD8 stalk and transmembrane domain followed by CD247 (aka CD3ζ), which provided the activation signal." (PMID 28822103, 2018). "Similarly, genes involved in T cell mediated immune response, such as CD3D, CD3E, CD3G, CD247 in the CD3-TCR complex and downstream effector ZAP70, were more rapidly repressed in LUSC than in LUAD, especially at the early cancer stage." (PMID 27863400, 2017). "Moreover, CD247, CD3G, HLA‐B, HLA‐C, and HLA‐F took part in various pathways, including Th1 and Th2 cell differentiation, PD‐L1 expression and PD‐1 checkpoint pathway in cancer, Th17 cell differentiation, antigen processing presentation, allograft rejection, and cell adhesion molecular." (PMID 35037412, 2022).
infection (4 papers, 2017 to 2024). The state of being infected such as from the introduction of a foreign agent such as serum, vaccine, antigenic substance or organism. "Hence, our data indicates that infection combined with deletion of Terc is associated with reduction of CD247 expression." (PMID 39607755, 2024). "In young WT mice gene expression levels of CD247 were increased with infection, likely due to proliferation and infiltration of T cells." (PMID 39607755, 2024). "To explore the role of macrophages in regulating T cell function during infection, we investigated whether AMs were sufficient to induce CD247/CD3ζ downregulation in T cells." (PMID 39607755, 2024). "(D) CD247 expression measured with flow cytometry of non-infected and infected T cells (left) and co-cultured T cells and AMs (right) of young WT (each n=3) and Tercko/ko mice (each n=3) after 24 hr post infection (hpi)." (PMID 39607755, 2024). "Interestingly, we could show that expression of CD247 is entirely absent in infected Tercko/ko mice, while in the non-infected Tercko/ko mice expression of CD247 could be detected after 24 hr of infection." (PMID 39607755, 2024). "The complete absence of CD247, an essential factor for downstream activation of the TCR, indicates aberrant T cell function of Tercko/ko mice during infection." (PMID 39607755, 2024).
bacterial infection (1 paper, 2024). "Our study provides the first evidence of the total absence of CD247 expression during acute bacterial infection and inflammation." (PMID 39607755, 2024).
hematopoietic cancers (1 paper, 2024). "In 3 independent studies, ZAP70, FYN, GRAP2, ITK, and CD247 (encoding CD3ζ) were highly upregulated in patients with T-ALL compared with individuals acting as healthy controls or people with other hematopoietic cancers, similar to our murine study." (PMID 38618957, 2024).
inflammation (1 paper, 2022). Aberrant reaction of the microcirculation characterized by movement of fluid and leukocytes from the blood into extravascular tissues. "IBD mice displayed colonic inflammation associated with weight loss and accumulation of MDSCs in the BM and spleen, which was accompanied by CD247 downregulation in splenic T cells with no change in CD3e expression, indicating chronic inflammation and T cell suppression." (PMID 35396510, 2022).
CD247 also shares sentences with these, for which no sentence is quoted: celiac disease (3 papers); colon carcinoma (2); HIV-1 infection (2); infectious disease (2); leukaemia (2); ovarian carcinoma (2); Type 1 diabetes (2); acute myeloid leukemia (1); Arthritis (1); atherosclerosis (1); Autoimmunity (1); B cell lymphopenia (1); B-cell lymphomas (1); Brain atrophy (1); breast invasive carcinoma (1); cervical squamous cell carcinoma (1); chronic obstructive pulmonary disease (1); cognitive disorder (1); connective tissue disorder (1); contact eczema (1); deficiencies (1); demyelinating disease (1); dermatomyositis (1); diffuse large B-cell lymphoma (1); endocervical adenocarcinoma (1); gastric cancer (1); HCMV infection (1); head and neck cancer (1); head and neck squamous cell carcinoma (1); hepatitis B (1).
A further 28 diseases each share a sentence with CD247 in 1 paper.